ZNF33B (zinc finger protein 33B)
Description:
May be involved in transcriptional regulation.
Synonyms: KOX2; ZNF11B; KOX31
Tractability: PROTAC: UniProt records ubiquitination sites on it; ubiquitination databases record sites on it.
Gene: Protein-coding gene on chromosome 10 (42,574,185 to 42,638,620, reverse strand). Ensembl gene ENSG00000196693.
Subcellular location: Nucleus
Subcellular location (Human Protein Atlas): Endoplasmic reticulum; Nucleoli fibrillar center; Vesicles
Pathways (Reactome):
Gene expression (Transcription): Generic Transcription Pathway
Gene Ontology:
Molecular function: protein binding; transcription cis-regulatory region binding
Biological process: negative regulation of transcription by RNA polymerase II; regulation of DNA-templated transcription
Cellular component: nucleus
Genetic constraint (gnomAD): Loss-of-function variants: 29 observed, 46.33 expected, observed/expected ratio (o/e) 0.63, 90% interval 0.47 to 0.85. The upper end of that interval is the gene's LOEUF score, 0.85, which puts it in group 3 of 6, group 1 being the genes least tolerant of losing a copy. Missense variants: 831 observed, 930.83 expected, observed/expected ratio (o/e) 0.89, 90% interval 0.84 to 0.94. Synonymous variants: 305 observed, 314.36 expected, observed/expected ratio (o/e) 0.97, 90% interval 0.88 to 1.07.
Homologues: Orthologues: chimpanzee ZNF33B (98% identical), macaque ZNF33B (95% identical). Paralogues in human: ZNF33A (93% identical), ZNF658 (46% identical), ZNF717 (44% identical), ZNF484 (43% identical), ZNF41 (42% identical), ZNF585B (41% identical), ZNF605 (41% identical), ZNF334 (41% identical), ZNF182 (40% identical), ZNF28 (40% identical), ZNF568 (40% identical), ZNF606 (40% identical), and 164 more.
Diseases named in the same sentence as ZNF33B in open-access papers:
ZNF33B is named in the same sentence as 3 diseases in open-access papers, as found by Europe PMC text mining. Sharing a sentence is not in itself a finding about the gene and the disease. The quoted sentences say what the papers report.
diabetes (1 paper, 2025). "ZNF33B is a transcriptional regulator associated with diabetes." (PMID 40386807, 2025).
Sepsis (1 paper, 2022). Sepsis is defined as life-threatening organ dysfunction caused by a dysregulated host response to infection. "This study shows that the lnc-ZNF33B-2:1 rs579501 CC genotype was associated with an increased risk of sepsis in the CHS population." (PMID 36419831, 2022). "In our case–control study, we investigated the associations between lnc-ZNF33B-2:1 gene polymorphism and sepsis risk in a southern Chinese population." (PMID 36419831, 2022). "In conclusion, the present study demonstrated that the lnc-ZNF33B-2:1 rs579501 C variant is a risk factor for sepsis in southern Chinese children." (PMID 36419831, 2022). "This research aims to evaluate the relationship between the candidate lnc-ZNF33B-2:1 allele and sepsis susceptibility and to assess the effect of sepsis-associated rs579501 on the susceptibility to sepsis in the southern Chinese population to better understand the public health risk." (PMID 36419831, 2022). "At first, it remained unclear how these lnc-ZNF33B-2:1 polymorphisms affect sepsis." (PMID 36419831, 2022). "The genotype analysis of the lnc-ZNF33B-2:1polymorphism revealed a remarkable difference in the carriers of the rs579501 genotypes exhibiting the CC allele (adjusted odds ratio = 2.026, 95% CI = 1.156–3.551, p = 0.0136), suggesting that rs579501 CC genotypes increased sepsis susceptibility." (PMID 36419831, 2022). "From the medical perspective, the lnc-ZNF33B-2:1 rs579501 CC genotype could be serving as a biochemical marker for sepsis." (PMID 36419831, 2022). "Genotype frequency distribution of lnc-ZNF33B-2:1 in sepsis cases and healthy controls." (PMID 36419831, 2022). "We also found that sepsis patients have a higher lnc-ZNF33B-2:1 level from the GEO database." (PMID 36419831, 2022). "Sepsis patients have higher lnc-ZNF33B-2:1 level (from the GEO database)." (PMID 36419831, 2022).
tumor (1 paper, 2023). "Among them, six lncRNAs (LASTR, lnc-LAMC2, lnc-ZNF33B, PVT1, MIR205HG, and ENTPD1-AS1) were previously reported to play critical roles in the tumor recurrence and metastasis." (PMID 36894542, 2023).